PLG (plasminogen)
Diseases named in the same sentence as PLG in open-access papers (continued):
Sharing a sentence is not in itself a finding about the gene and the disease.
colon cancer (6 papers, 1999 to 2025). "Increased expression of PLAUR and components of the plasminogen activation system correlate with malignancy and are associated with metastasis in several types of cancer, including colon cancer (61, –, 64)." (PMID 28717003, 2017). "In addition, tetranectin exhibited a similar IHC staining pattern as plasminogen in colon cancer and co-localized with plasminogen/plasmin at the invasive front of cutaneous melanoma lesions, indicating a coordinated role of these proteins in the invasive process." (PMID 20957082, 2010). "While they operate through different mechanisms and serve distinct functions, it is likely that they indirectly influence each other during metastatic processes and that the genes in this cluster which also include PLG and ESR1 constitute a 5hmC metastatic signature for colon cancer." (PMID 40241172, 2025).
dysplasminogenemia (6 papers, 2015 to 2024). "The East Asian abundant PLG/A601T variant and six other rare and ultra-rare PLG missense variants have been associated with dysplasminogenemia." (PMID 38984351, 2024). "PLG/A601T is the most reported PLG missense variant associated with dysplasminogenemia and is present in up to 4% of East Asian individuals." (PMID 38984351, 2024). "PDII, also known as dysplasminogenemia is characterized by normal or slightly lower PLG antigen level with a diminished or abnormal activity." (PMID 38984351, 2024). "Accordingly, these three patients were tentatively diagnosed with dysplasminogenemia, and subsequent PLG gene sequencing led to the identification of the heterozygous Ala620Thr mutation in all three patients." (PMID 37065478, 2023). "Two gene mutations—MTHFR (5,10-methylenetetrahydrofolate reductase gene) 677 C>T and PLG (plasminogen) 1858G>A—were identified as possible genetic determinants of the homocysteine level and dysplasminogenemia, respectively." (PMID 27057875, 2016). "Decreased plasminogen activity indicates dysplasminogenemia." (PMID 35244080, 2022). "Our report supports the previous findings that the isolated PLG Ala620Thr variant does not confer a significant risk of thromboembolism and thus contributes substantially to research on dysplasminogenemia." (PMID 35244080, 2022). "Dysplasminogenemias are generally considered to be disorders caused by PLG variants but may not necessarily lead to disease or thrombotic risk." (PMID 38984351, 2024).
hemorrhage (6 papers, 2008 to 2025). Loss of blood from the vascular compartment to the exterior or into nonvascular body space as a result of rupture or severance of the blood vessels. "TXA, a lysine analogue inhibiting plasminogen activation and providing clot stability, has been used to reduce hemorrhage." (PMID 39425234, 2024). "Tranexamic acid has anti-fibrinolytic properties via competitive inhibition of plasminogen activation making it a logical approach to promote hemostasis in cases of post-tonsillectomy hemorrhage." (PMID 34436991, 2021). "IA is characterized by hemorrhage and tissue destruction, which are mediated by the plasminogen system." (PMID 18566672, 2008). "Dengue virus infection can induce PLG cross-reactive autoantibodies that may enhance PLG activation and contribute to hemorrhage in patients with dengue hemorrhagic fever or shock syndrome." (PMID 40377310, 2025).
multiple sclerosis (6 papers, 2014 to 2024). A progressive autoimmune disorder affecting the central nervous system resulting in demyelination. "Trace amounts of plasminogen have been reported in normal human cerebrospinal fluid (CSF), whereas raised concentrations have been detected in patients with meningitis, subarachnoid haemorrhage and multiple sclerosis." (PMID 25220760, 2014). "In parallel, plasminogen was investigated in CSF from patients with Guillain-Barré syndrome (n = 15), multiple sclerosis (n = 19) and noninflammatory neurological diseases (n = 8)." (PMID 25220760, 2014). "Plasminogen in human CSF was higher in Guillain-Barré syndrome (median = 1.28 ng/μl (interquartile range (IQR) = 0.66 to 1.59)) as compared to multiple sclerosis (median = 0.3 ng/μl (IQR = 0.16 to 0.61)) and to noninflammatory neurological diseases (median = 0.27 ng/μl (IQR = 0.18 to 0.35))." (PMID 25220760, 2014).
Obesity (6 papers, 2011 to 2025). Accumulation of substantial excess body fat. "Genetic variants in SLC39A8 have previously been associated to several cardiovascular risk factors such as HDL-cholesterol, blood pressure, obesity, and activation of plasminogen." (PMID 23372645, 2013). "Active ingredients in WP, such as oxidized glutathione, may improve symptoms of HFD-induced obesity by acting on targets such as EGFR, NOS3, MMP2, PLG, PTGS2, and AR." (PMID 38162665, 2023).
Parkinson disease (6 papers, 2016 to 2024). A progressive degenerative disorder of the central nervous system characterized by loss of dopamine producing neurons in the substantia nigra and the presence of Lewy bodies in the substantia nigra and locus coeruleus. "The underexpressed proteins were annotated to fructose galactose metabolism, apoptosis signaling pathway, plasminogen activating cascade, Parkinson’s disease, gonadotropin releasing hormone receptor pathway, glycolysis and blood coagulation pathways." (PMID 26988818, 2016).
Arthritis (5 papers, 2010 to 2023). Inflammation of a joint. "We have previously shown that plasminogen levels are important for the incidence and severity of collagen II-induced arthritis." (PMID 21931850, 2011). "The plasminogen activation pathway is dysregulated in arthritis." (PMID 23259760, 2012).
conjunctivitis (5 papers, 2016 to 2025). Inflammation of the conjunctiva of the eye. "Hereditary PLG deficiency can be classified into two subtypes: Type I (reduced activity and antigen levels) typically causes ligneous conjunctivitis, while Type II (reduced activity with normal antigen levels) predisposes to venous thromboembolism." (PMID 41398600, 2025). "Plasminogen is considered a key player in fibrinolysis processes, and in view of a bench-to-bedside translation, we focused on the aerosolization of an orphan medicinal product (OMP) for ligneous conjunctivitis: human plasminogen (PLG-OMP) eye drops." (PMID 33260813, 2020). "However, mice deficient for both PLG and fibrinogen did not develop ligneous conjunctivitis thereby linking PLG/plasmin-mediated clearance of fibrin as a regulatory mechanism for this disease." (PMID 38984351, 2024). "Presently, pharmaceutical grade plasma-derived plasminogen (PLG) is available as eye drops (Kedrion S.p.A.)and currently used as an orphan medicinal product (OMP), according to Italian law 648/96, for the treatment of ligneous conjunctivitis." (PMID 33260813, 2020).
dengue (5 papers, 2014 to 2025). "Plasminogen was increased in the pre-COVID-19 Dengue group compared to healthy controls, while TFPI levels did not differentiate the groups." (PMID 41305453, 2025). "Previous research identified antithrombin antibodies in dengue, mostly IgG targeting DENV NS1 and plasminogen." (PMID 41305453, 2025). "Furthermore, envelope proteins from viruses isolated from patients with severe dengue were more efficient at activating plasminogen than the envelope proteins isolated from patients with non-severe dengue." (PMID 31726374, 2019).
endothelial dysfunction (5 papers, 2014 to 2025). In vascular diseases, endothelial dysfunction is a systemic pathological state of the endothelium (the inner lining of blood vessels) and can be broadly defined as an imbalance between vasodilating and vasoconstricting substances produced by (or acting on) the endothelium. "In this setting, endothelial dysfunction results in either low-grade secretion of tissue plasminogen activator (tPA) or enhanced plasminogen activation on the surface of the endothelial cell by urokinase or UPA (urokinase-type plasminogen activator) in subjects with Fabry disease." (PMID 24959362, 2014). "In our study, among differentially expressed proteins were PLG, SERPING1, SERPINC1, APOA2, FGB, A2M, which are related to endothelial dysfunction, coagulation processes and pro-atherogenic alteration mechanisms." (PMID 29755368, 2018).
fibrosarcoma (5 papers, 2007 to 2024). A malignant mesenchymal fibroblastic neoplasm affecting the soft tissue and bone. "Tumor growth of both Lewis lung carcinoma (LLC) and T241 fibrosarcoma cells was unaffected by plasminogen deficiency following injection into the dorsal skin of mice but was significantly reduced in plasminogen‐deficient mice if tumor cells were injected into the footpad." (PMID 37971174, 2024). "We previously observed that plasminogen activation is substantially reduced in p11-depleted cancer cells such as colorectal, fibrosarcoma, pancreatic, and lung." (PMID 33297495, 2020). "We have reported that p11 regulates plasminogen activation on the cell surface of many cancer cells including fibrosarcoma, colorectal, lung, and pancreatic cells." (PMID 33297495, 2020).
glioma (5 papers, 1978 to 2025). A benign or malignant brain and spinal cord tumor that arises from glial cells (astrocytes, oligodendrocytes, ependymal cells). "uPA is a protease, which is overexpressed in high-grade gliomas, that converts plasminogen to plasmin with a better efficacy when anchored to its receptor, uPAR." (PMID 36980765, 2023). "Plasminogen is produced by glioma cells and converted to plasmin by the protease uPA, which is activated by the uPA receptor expressed on astrocytes." (PMID 34690699, 2021). "Using a fibrin-agarose-overlay technique, high levels of plasminogen-dependent fibrinolytic activity have been demonstrated in cell lines derived from an ethylnitrosourea-induced glioma of the rat brain." (PMID 638021, 1978). "The collagen and glycoprotein profiles in pediatric HGGs showed partial overlap with adult tumors, with three of the top glycoproteins in adult gliomas (VTN, TNR, and PLG) also among the most highly expressed proteins in pediatric gliomas." (PMID 40517137, 2025).
prion disease (5 papers, 2007 to 2025). A transmissible disease that is caused by a protein that is able to induce abnormal folding of normal cellular proteins, leading to characteristic spongiform brain changes, which are associated with neuronal loss without an inflammatory response. "Previous studies have reported that plasminogen plays a key role in the acceleration of prion disease progression." (PMID 40302732, 2025). "There have been a number of studies published describing a role for plasminogen activation in prion disease, but these studies have been focussed on tPA." (PMID 19459212, 2009). "An increase in total plasminogen activation with progression of prion disease is apparent in both soluble and membrane fractions (respectively)." (PMID 19459212, 2009). "The aim of this study was to use HR-US to characterize the real-time interactions between plasminogen coated beads and PrPSc and to determine if this approach could be applied to the identification of animals affected by prion diseases." (PMID 17659071, 2007). "Furthermore, several in vitro studies have reported that interaction between PrPSc and plasminogen may favor PrPSc replication and propagation and that t-PA displays higher expression and activity in mouse models of prion disease." (PMID 35416570, 2022). "Furthermore, disruption of the PrP-plasminogen interaction with L-lysine and its polymers successfully inhibited PrPSc formation in PMCA, cell culture, and mouse models of prion disease." (PMID 36117913, 2022).
pulmonary embolism (5 papers, 2016 to 2024). The obstruction of the pulmonary artery or one of its branches by an embolus, sometimes associated with infarction of the lung. "Alteplase is especially applied for intravenous thrombolysis (e.g., in acute ischemic stroke or pulmonary embolism) due to the efficient conversion of plasminogen to plasmin in the presence of fibrin clots." (PMID 39337591, 2024). "In the clinic, streptokinase (trade name Streptase) is used to treat acute evolving transmural myocardial infarction, pulmonary embolism, deep vein thrombosis, arterial thrombosis, and occlusion of the arteriovenous cannula by converting plasminogen to plasmin." (PMID 38556942, 2024). "In the setting of a massive pulmonary embolism leading to hemodynamic instability, thrombolysis with plasminogen-activating fibrinolytic agents, catheter-based thrombus reduction via pharmacological and/or mechanical methods, or surgical thromboembolectomy can be considered." (PMID 26904303, 2016).
type 2 diabetes (5 papers, 2009 to 2023). "BMI levels were positively correlated with plasminogen-activator network (t-PA Ag), as well as plasminogen activator inhibitor-1 (PAI-1 Ag) concentration, and BMI can be associated with high plasma levels of PAI-1 Ag in Type 2 Diabetes." (PMID 31623288, 2019). "The non-CHD indications of clinically used drugs included dyslipidemias (PPARA), type 2 diabetes (PPARG and NDUFA13), autoimmune diseases (TNF), neoplasms (RAF1 and PSMA5), circulatory disorders (ABCA1, PLG, ITGB3, and F2), and alcohol-dependency (ALDH2)." (PMID 34675202, 2021).
vasculitis (5 papers, 2018 to 2024). "Anti-plasminogen antibodies (α-PLG) were previously detected in a subpopulation of anti-neutrophil cytoplasmic antibody (ANCA)-associated vasculitis (AAV) patients, showing a relation to renal lesions and outcome." (PMID 30419041, 2018). "Furthermore, our results have clarified the association between HLA and this form of vasculitis, and substantiated the role of another established giant cell arteritis-associated locus, the PLG gene." (PMID 38734017, 2024). "Additionally, a very similar model has independently been proposed to explain the etiology of anti-neutrophil cytoplasm antibody (ANCA) vasculitis as a result of the immune response to proteinase 3, collagen, and their complementary antigens, which include plasminogen." (PMID 37569555, 2023). "Moreover, five of nine patients with VTE in the PR3-ANCA group exhibited anti-plasminogen antibodies; in contrast, these were absent in patients with MPO-ANCA vasculitis and thrombosis." (PMID 33909191, 2021).
Cirrhosis (4 papers, 2016 to 2025). A chronic disorder of the liver in which liver tissue becomes scarred and is partially replaced by regenerative nodules and fibrotic tissue resulting in loss of liver function. "Our study demonstrated that TSP-1, Gal-3, and Cys-C independently increased the risk of death in compensated cirrhosis, whereas albumin and plasminogen activity could act as protective factors." (PMID 40417691, 2025). "Progressive cirrhosis severity is characterized by declining hepatic derived factors (plasminogen, FXIII) and increasing extrahepatic factors (tPA, TAFI), driving a hypofibrinolytic, prothrombotic state." (PMID 41228207, 2025). "Infected patients with decompensated cirrhosis present mixed fibrinolytic changes, with lower plasminogen levels, higher levels of tissue plasminogen activator, and similar levels of plasmin–antiplasmin complexes compared to non-infected patients." (PMID 37685826, 2023).
Hypercholesterolemia (4 papers, 2016 to 2024). An increased concentration of cholesterol in the blood.
Hypofibrinogenemia (4 papers, 2021 to 2025). Decreased concentration of fibrinogen in the blood. "Hypofibrinogenemia in HLH is caused by plasminogen activators released by activated macrophages, increasing plasmin concentration, leading to increasing cleavage of fibrinogen." (PMID 33803997, 2021).
Insulin resistance (4 papers, 2021 to 2023). Increased resistance towards insulin, that is, diminished effectiveness of insulin in reducing blood glucose levels. "The data indicate that mGluR5 activation is associated with insulin resistance and increased PLG expression." (PMID 37314019, 2023). "We showed that high glutamate levels induced insulin resistance, which subsequently increased the expression of PLG in the liver." (PMID 37314019, 2023). "Among glutamate‐related genes, plasminogen (PLG) levels were most significantly increased in several environments in which insulin resistance was induced, and was also upregulated by glutamate." (PMID 37314019, 2023). "We further investigated the alteration in PLG expression after the induction of endoplasmic reticulum (ER) stress and mitochondrial dysfunction, which are closely related to insulin resistance." (PMID 37314019, 2023). "In addition, it increases the secretion of leptin, resistin, and inhibitor-1 of plasminogen activation, which promotes insulin resistance." (PMID 34568974, 2021). "In addition, the expression of PLG in the liver tissue of C57BL6 mice, in which insulin resistance was induced by a high‐fat diet, was significantly increased compared to that in the control group." (PMID 37314019, 2023).
leptospirosis (4 papers, 2010 to 2023). A contagious bacterial infection caused by spirochetes of the genus Leptospira. "This protein has been detected on the surface of Leptospira interrogans (the spirochete which is the aetiological agent of leptospirosis) and it is related to the binding with the host plasminogen." (PMID 28522991, 2017). "In addition, we show that plasminogen (PLG)/plasmin (PLA) generation on the surface of leptospires can lead to Fg degradation, showing evidence of possible route of fibrinolysis in leptospirosis." (PMID 24009788, 2013).
meningitis (4 papers, 2013 to 2025). A disorder characterized by acute inflammation of the meninges of the brain and/or spinal cord. "Based on our findings, we suggest that PLG may be the cause of meningitis in EV-A71 infections." (PMID 40377310, 2025). "pbsP has been shown to contribute to GBS vaginal colonization, meningitis, and diabetic wounds through the binding of components of the extracellular matrix such as plasminogen and fibrinogen and adherence to both epithelial and endothelial cells, as is the case with PI-2b (14, 53, –, 57)." (PMID 37905908, 2023). "Moreover, our results suggest that therapies aimed at neutralizing the activation of plasminogen system at GBS surface could be beneficial in preventing development of meningitis." (PMID 23658816, 2013). "We hypothesized that modulation of the host plasminogen system by GBS could play a role in the penetration of the BBB and development of meningitis." (PMID 23658816, 2013).
skin infection (4 papers, 2007 to 2021). An inflammatory process affecting the skin, caused by bacteria, viruses, parasites, or fungi. "Staphylokinase, which mediates the digestion of fibrin clots via activation of plasminogen to plasmin, has been shown to promote the establishment of S. aureus skin infections, but at the same time decrease the severity of the disease." (PMID 33546401, 2021). "We evaluated the role of SAK-mediated plasminogen activation in a subcutaneous S. aureus skin infection model in mice." (PMID 25515118, 2014). "We studied the role of plasminogen activation by SAK in a skin infection model in mice and evaluated the impact of alpha-2-antiplasmin (α2AP) deficiency on the spreading and proteolytic activity of S. aureus skin infections." (PMID 25515118, 2014). "An animal model of pyoderma suggests that skin infection with these strains requires streptokinase and PAM-bound plasminogen." (PMID 18217553, 2007).